OTX2 (orthodenticle homeobox 2)
Diseases named in the same sentence as OTX2 in open-access papers (continued):
Sharing a sentence is not in itself a finding about the gene and the disease.
retinal degeneration (9 papers, 2011 to 2025). Degeneration of the retina. "Moreover, investigating the relationship of OTX2 and autophagy in RP pathogenesis would be valuable in further delineating the mechanisms underlying retinal degeneration." (PMID 40956390, 2025). "Similarly, two autosomal dominant families with heterozygous pathogenic variants in OTX2 with only retinal degeneration patterns were previously reported." (PMID 34327195, 2021). "This is necessary to note, because this Crx-Otx2 interaction can be a source of early-onset retinal degeneration." (PMID 40558514, 2025). "Finally, Otx2 induced photoreceptor precursor cells were injected into subretinal space of N‐methyl‐N‐nitrosourea induced rat model of retinal degeneration and partially recovered retinal degeneration in the rats." (PMID 30451368, 2019). "Finally, Otx2 induced photoreceptor precursor cells were injected into subretinal space of N‐methyl‐N‐nitrosourea (MNU) induced rat model of retinal degeneration to test the in vivo efficacy of Otx2 induced photoreceptor‐like cells to recover retinal degeneration." (PMID 30451368, 2019). "Collectively, these findings emphasize the role of OTX2 in regulating the human TYR gene, with implications for inter-individual differences in melanin synthesis, retinal development, and function as well as susceptibility to retinal degeneration associated with aging." (PMID 22259223, 2012). "Since many of the Otx2 CKO down-regulated genes at P12 were photoreceptor-associated genes, we supposed that mutations of human homologs of these down-regulated genes may be responsible for retinal degeneration diseases." (PMID 21602925, 2011). "Potential interacting molecules involved in retinal degeneration or visual cycle, including MINDY3, EPG5, miR‐548b‐3p, OTX2, miR‐519d, LRAT, and NR2E3, were selected based on the STRING and miRDB (MicroRNA Target Prediction Database) databases." (PMID 40956390, 2025). "However, RPE-specific deletion of Sox9 does not induce retinal degeneration and in fact results in Otx2 upregulation, suggesting that Sox9 is not an upstream regulator of Otx2 in this context." (PMID 41190718, 2025).
coloboma (7 papers, 2009 to 2024). An abnormality in which a part of a structure in one or both eyes is missing. "In eye genetic disorders (Microphtalmia/Anophtalmia/ Coloboma-Optic Nerve Hypoplasia, MAC-ONH), only between 40 and 50% of cases are explained by mutations within the exomes of several genes, including SOX2, OTX2 and PAX6 among the most frequently mutated." (PMID 35887306, 2022).
Retinal dystrophy (7 papers, 2009 to 2025). Retinal dystrophy is an abnormality of the retina associated with a hereditary process. "Differential diagnoses of reduced EOG light-rise include OTX2-associated retinal dystrophy, and autosomal dominant vitreoretinochoroidopathy (ADVIRC) due to selected bestrophin-1 (BEST1) variants." (PMID 40455352, 2025). "While the variable phenotype and natural history of PRPH2- and OTX2-associated retinal dystrophies have been described in large cohorts, clinical features of CTNNA1-associated retinal dystrophy are less well studied." (PMID 40455352, 2025). "This case adds further support for a role of OTX2 both in retinal development and pituitary function, and highlights a novel retinal dystrophy phenotype seen in association with mutations in OTX2." (PMID 19956411, 2009). "Mutations in OTX2 have been reported in association with major developmental malformations of the eye, with retinal dystrophies such as LCA, and with pituitary dysfunction and seizure activity in some cases." (PMID 19956411, 2009). "OTX2-associated retinal dystrophy can also present with reduced EOG light rise." (PMID 40455352, 2025).
Anxiety (6 papers, 2021 to 2025). Intense feelings of nervousness, tension, or panic often arise in response to interpersonal stresses. "In this study, we found that chronic peripubertal stress applied between P30 and P36, which strongly induces a high susceptibility to anxiety in male mice through hyperactivation of Otx2+ IPN neurons, has a much weaker effect in females." (PMID 40893346, 2025). "Because of this presence of OTX2 in several structures implicated in the regulation of anxiety-related behaviors, we tested the expression of different genes in these regions to identify possible altered pathways due to potentially reduced OTX2 level." (PMID 33963285, 2021). "Previously, adult male mice subjected to early-life stress were found susceptible to anxiety-like behaviors, with accompanying OTX2 expression changes in ventral tegmental area or choroid plexus." (PMID 33963285, 2021). "Although Otx2+ neurons and the PNNs surrounding them are implicated in anxiety regulation, the precise mechanisms remain unclear." (PMID 40893346, 2025). "However, stress disrupts this maturation, and consequently—or in parallel—induces activity in Otx2+ neurons of the med-cIPL and cIPC regions, leading to persistent circuit dysregulation, increased stress sensitivity, and greater susceptibility to anxiety." (PMID 40893346, 2025). "On this basis, we hypothesized that PNNs could influence anxiety susceptibility by imprinting stress-induced hyperactivation in Otx2+ IPN neurons during a critical period." (PMID 40893346, 2025). "Taken together, OTX2 synthesis by the choroid plexus followed by its secretion into the cerebrospinal fluid is an important regulator of anxiety-related phenotypes in the mouse." (PMID 33963285, 2021). "This ChP-specific expression also rescued PV cell staining in the mPFC, and positions ChP OTX2 as a regulator of anxiety-related phenotypes." (PMID 33963285, 2021). "This does not exclude other extra-cortical sources, in particular the pineal gland, but establishes that the ChP, through the synthesis and secretion of OTX2 is an important regulator of anxiety-related phenotypes in the mouse." (PMID 33963285, 2021). "These experiments suggest that OTX2 expression in the ChP is sufficient to restore a normal anxiety-related behavior in the Otx2-het mouse with accompanying changes in mPFC PV cell populations." (PMID 33963285, 2021). "In this study, we provide evidence for a role of Otx2 in the regulation of anxiety-like behavior and show that OTX2 secreted from the ChP into the CSF plays a role in this regulation." (PMID 33963285, 2021). "Supporting this hypothesis, a recent study has shown that neurons expressing DDR3 and showed to largely correspond to Otx2+ lat-cIPL are activated under anxiogenic environment to counteract anxiety." (PMID 40893346, 2025). "Blocking OTX2-PNN interaction or sequestering OTX2 in the CSF in adult mice can promote ocular dominance plasticity, while overexpression of OTX2 in the choroid plexus can rescue plasticity-dependent anxiety-like behavior deficits regulated in the mPFC." (PMID 35601531, 2022). "Likewise, experimentally inducing a lowering of the transfer of OTX2 from the choroid plexus to the PV neurons in rodents, results in anxiety-related phenotypes." (PMID 36590919, 2022). "Periodic separation of mouse pups from their mothers, during a critical period from postnatal day 10 (P10) to P20, results in a transient decrease in Otx2 expression in the VTA that leads directly to latent anxiety- and depressive-related phenotypes in male adults." (PMID 33963285, 2021). "Our finding that reducing OTX2 in the CSF can reduce anxiety-related behavior in the adult suggests that the mechanisms involved may differ from those at work in the maternal separation paradigms." (PMID 33963285, 2021).
Anxiety (continued). "However, we found reduced expression of parvalbumin in medial prefrontal cortex, which could be rescued in part by adult overexpression of Otx2 specifically in choroid plexus, resulting in increased anxiety-like behavior." (PMID 33963285, 2021). "In a separate study of anxiety-like behavior induced by maternal separation and early weaning, it was proposed that Otx2 upregulation in the ChP and increased OTX2 levels in the ventral hippocampus inhibitory interneurons may participate in the anxiety-related phenotype." (PMID 33963285, 2021). "Our model supports the hypothesis that Otx2 loss- and gain-of-function in the adult ChP can regulate anxiety-related behavior in the mouse, although it does not preclude that other models may extend the role of Otx2 expression, during specific developmental periods, to other pathologies." (PMID 33963285, 2021). "The expression patterns of OTX2 in response to weaning and MIA effects is in agreement with reports of under-expression in the amygdala of rats exposed to neonatal stress and displaying anxiety as adults." (PMID 33856433, 2021). "Interestingly, recent experiments strongly suggest that OTX2 imported in PNN-enwrapped PV cells in the mPFC and in the ventral hippocampus might regulate anxiety-like behaviors." (PMID 33963285, 2021). "Otx2 is expressed in the adult VTA, and the projections of the VTA into several target structures, including the hippocampus, nucleus accumbens, amygdala, and the mPFC, may be involved in anxiety regulation." (PMID 33963285, 2021). "Indeed, another maternal separation paradigm that results in excessive adult anxiety-related behavior implicates altered ventral hippocampus PV cell plasticity, which is accompanied by increased OTX2 in the ChP and non-cell-autonomous OTX2 in the ventral hippocampus." (PMID 33963285, 2021).
Parkinson disease (6 papers, 2012 to 2025). A progressive degenerative disorder of the central nervous system characterized by loss of dopamine producing neurons in the substantia nigra and the presence of Lewy bodies in the substantia nigra and locus coeruleus. "Furthermore, Otx2 also reportedly targets genes encoding mitochondrial components, and these Otx2-bound genes are enriched in pathways, including Alzheimer’s, Huntington’s, and Parkinson’s diseases in the mouse developmental/juvenile cortex." (PMID 39083515, 2024). "In addition, due to the expression of OTX2 in the central nervous tissue, and the presence of tyrosinase in the substantia nigra and other parts of the brain, the question of the role of OTX2 and the polymorphic site 3 in susceptibility to Parkinson disease arises." (PMID 22259223, 2012). "For a few transcription factors of this family, primarily ENGRAILED1, ENGRAILED2 and OTX2, their physiological functions have led to therapeutic strategies in animal models of human diseases, including Parkinson’s disease, amyotrophic lateral sclerosis, amblyopia and anxiety-related disorders." (PMID 38550565, 2024). "A series of genes, including mCherry and various combinations of the neural transcription factors LMX1a, FOXA2 and OTX2, were inserted in recipient cell lines derived from H9 ESC, as well as iPSC lines derived from a Parkinson’s disease patient and a normal sibling control." (PMID 24304893, 2014).
developmental delay (5 papers, 2014 to 2021). "Patients harboring OTX2 mutations present a microphthalmia syndrome associated to multiple features resembling those of DS such as developmental delay, hypotonia or short stature." (PMID 25955728, 2015). "In addition, our data suggest that the majority of patients with OTX2 mutations have developmental delays." (PMID 33950863, 2021). "OTX2 mutations are associated with severe ocular phenotypes, seizures, and developmental delay." (PMID 32850550, 2020).
retinal diseases (5 papers, 2010 to 2025). "It will be important to discover what are the targets of Otx2 in the mature retina and to look for de novo OTX2 mutations in patients suffering specifically from late onset retinal diseases." (PMID 20657788, 2010). "We found that three human retinal disease loci were mapped in close proximity to the markedly down-regulated genes in the Otx2 CKO retina." (PMID 21602925, 2011). "Therapeutic inhibition of inflammation or restoration of OTX2 expression might help restore RPE function in retinal diseases with a subretinal inflammatory component." (PMID 27660103, 2017). "Furthermore, we identified several retinal disease candidate genes among the genes down-regulated in the Otx2 CKO retina based on information from RetNet's mapped retinal disease loci." (PMID 21602925, 2011). "Furthermore, we identified three human retinal disease loci mapped in close proximity to certain down-regulated genes in the Otx2 CKO retina including Ccdc126, Tnfsf13 and Pitpnm1, suggesting that these genes are possibly responsible for these diseases." (PMID 21602925, 2011). "Therefore it is quite possible that changes in noncoding sequences regulating Otx2 transcription might lead to retinal disease." (PMID 20657788, 2010). "Additionally, the transplantation of RPE cells genetically modified to express OTX2, a critical transcription factor for RPE development, has shown promise in treating retinal diseases such as AMD." (PMID 40867611, 2025). "Therapeutic restoration of OTX2 expression might help revive RPE and visual function in retinal diseases such as AMD." (PMID 27660103, 2017). "We show that in the RPE, the primary tissue affected in AMD, LHX2 is required for OTX2 expression and both co-bind multiple cis-regulatory regions controlling the transcriptional program that defines RPE identity, including genes involved in monogenic and complex retinal diseases." (PMID 36649236, 2023).
brain tumor (4 papers, 2011 to 2023). "Among all the tested combinations, we observed reduced mice survival with Gfi1 + c-MYC (GM) and Otx2 + c-MYC (OM) genes overexpression and formation of brain tumors." (PMID 31996670, 2020). "There were no histological indications of brain tumors in moribund or asymptomatic GFAP:Hi-Otx2 mice aged for up to one year." (PMID 22558385, 2012).
schizophrenia (4 papers, 2014 to 2022). A major psychotic disorder characterized by abnormalities in the perception or expression of reality. "Otx2-bound genes were associated with human diseases such as schizophrenia as well as critical periods." (PMID 28620275, 2017). "Interestingly, these pathways are linked to schizophrenia, implying that Otx2 is involved in this disease." (PMID 28620275, 2017). "OTX2 is also related to thalamic development and “dysfunctional thalamus-related networks” have been reported in schizophrenia." (PMID 25506321, 2014). "OTX2 regulates PNN and PV expression levels, PNN density is found to be low in the prefrontal cortices of schizophrenia patients, while weakened PV circuits in the mPFC cause deficits in behavioral aspects of schizophrenia patients." (PMID 33963285, 2021). "We think OTX2 stands out because it appears to play a role both in CPB and schizophrenia." (PMID 25506321, 2014).
asthma (3 papers, 2017 to 2020). "Notable hypermethylated probe-IDs with gene names included AGR2 (Anterior Gradient Protein 2), which plays a role in asthma and mucin production, and OTX2 (Orthodenticle Homeobox 2), which interacts with nitric oxide." (PMID 32850550, 2020). "The role of OTX2 in asthma and response to steroid treatment is unknown." (PMID 29028809, 2017). "The hypermethylated genes have roles in asthma (VGLL4, AGR2), neurologic development (AGAP1, OTX2), and immune regulation (SCAMP5, SLC11A1)." (PMID 32850550, 2020).
colitis (3 papers, 2020 to 2022). Inflammation of the colon. "In our study, we used AOM/DSS to induce colitis‐associated CRC model, so our study implies that Otx2 represses colitis‐associated CRC through regulating gene expression, such as IFITM family genes." (PMID 35712778, 2022). "Experimentally-induced colitis upregulates the number of myenteric neurons expressing OTX2 both on site and distantly." (PMID 32095330, 2020). "In the present study, we investigated possible changes in the expression of homeoprotein transcription factors, orthodenticle homeobox protein 1 and 2 (OTX1 and OTX2), in the rat myenteric plexus after an experimentally-induced colitis." (PMID 32095330, 2020). "In this study, we evaluated OTX1 and OTX2 expression in the rat small intestine and distal colon myenteric plexus after intrarectal dinitro-benzene sulfonic (DNBS) acid-induced colitis." (PMID 32095330, 2020). "In good agreement, in the present study we show a significant increase of both OTX1 and OTX2 mRNA and protein levels in LMMP preparations of the rat small intestine and distal colon myenteric plexus after DNBS-induced colitis." (PMID 32095330, 2020). "After DNBS-induced colitis, analogously to OTX1, up-regulation of OTX2 in the rat myenteric plexus was evidenced also for the transcript and protein, by means of qRT-PCR and western immunoblotting." (PMID 32095330, 2020). "In our study, we aim for the first time to evaluate possible changes of OTX1 and OTX2 expression in rat colon myenteric ganglia, after dinitro-benzene sulfonic (DNBS) acid-induced colitis, by means of molecular biology and morphological approaches." (PMID 32095330, 2020). "In order to confirm the immunofluorescence data reflecting an up-regulation of OTX1 and OTX2 in the rat small intestine and colon myenteric plexus after DNBS-induced colitis, we evaluated the levels of mRNA and proteins of both homeobox proteins in LMMP preparations." (PMID 32095330, 2020). "Accordingly, in the present study, a substantial involvement of iNOS and nNOS in colitis-induced upregulation of OTX1 and OTX2, respectively, is suggested by the superimposition of OTX1 with iNOS and OTX2 with nNOS immunostaining, in myenteric ganglia of both regions studied." (PMID 32095330, 2020).
Leber congenital amaurosis (3 papers, 2009 to 2024). Leber congenital amaurosis (LCA) is a retinal dystrophy defined by blindness and responses to electrophysiological stimulation (Ganzfeld electroretinogram (ERG)) below threshold, associated with severe visual impairment within the first year of life. "In particular, the Leber congenital amaurosis (LCA) gene OTX2 showed high expression at the beginning of the trajectory of both PRs and BCs." (PMID 39055259, 2024). "Leber congenital amaurosis and macular degeneration were enriched in C0, which specifically expressed RPE65, OTX2, LRAT, and BEST1." (PMID 33072724, 2020).
lung carcinoma (3 papers, 2013 to 2023). "Similarly to BARHL2, OTX2 has been found aberrantly methylated in epithelial tumours including breast and lung cancer." (PMID 37301955, 2023). "BARHL2, DMRTA2, OTX1 and OTX2 were identified as DNA methylation markers for lung cancer." (PMID 35313869, 2022). "EVX1 and OTX2 were identified as methylated in NSCLC and lung cancer." (PMID 24369052, 2013).
microcephaly (3 papers, 2018 to 2025). A congenital or acquired developmental disorder in which the circumference of the head is smaller than normal for the person's age and sex. "Similarly, mutations in OTX2 have been described in patients with eye defects, variable congenital hypopituitarism, and one individual with microcephaly." (PMID 38094004, 2023). "Despite the low prevalence of microcephaly in patients with OTX1 or OTX2 variants, it is worth focusing on these OTX genes as potential causal genes for microcephaly, given the severity of the brain phenotypes observed in mice." (PMID 38094004, 2023). "In this study, I focus on several homeobox genes (ARX, LHX2, MEIS2, NKX2-1, OTX1, OTX2, and PAX6) implicated in the pathogenesis of microcephaly." (PMID 38094004, 2023).